CDKN2A (cyclin dependent kinase inhibitor 2A)
Diseases named in the same sentence as CDKN2A in open-access papers (continued):
Sharing a sentence is not in itself a finding about the gene and the disease.
cervical carcinoma (continued). "TSGs such as RASSF1, CDKN2A, DAPK, APC and p14ARF are aberrantly methylated in NSCLC as well as other cancers, namely head and neck cancer (HNC), prostate cancer and cervical cancer." (PMID 34991275, 2019). "The methylation rates of IFN-γ, FHIT, MGMT, CDKN2A, SALL3, and gene promoters were significantly higher in cervical cancer tissues than those in CIN and normal cervical tissues, which are related to the progression of cervical oncogenesis." (PMID 29850477, 2018). "Among genetic and epigenetic factors, inactivation of the p16ink4a gene (cyclin-dependent kinase inhibitor 2a, CDKN2A) by point mutations, deletions, and methylation, has been reported in a large number of other cancers, an event that might also contribute to cervical cancer development." (PMID 30569945, 2018). "Although Gal-7 affects the specific cervical cancer networks in different ways, we identified a group of eight molecules that are regulated in both cell lines: CRYAB, TACSTD2, BCL-3, COX19, OASL, CDKN2A/p14ARF, NIBAN/FAM129A, and FST." (PMID 27558259, 2016). "Significant promoter hypermethylation has been reported for both CDKN2A and CDKN2B in cervical cancer patients of North Indian origin." (PMID 24790823, 2014). "Cervical cancer and SCLC, which are known to be the tumor types with a higher frequency of dysfunctional RB1, showed lower CCND1/CDKN2A ratios compared with endometrial and gastric cancers." (PMID 21447152, 2011). "CDKN2A is a canonical proliferation marker that is also a well‐documented biomarker for HPV infection, with expression levels increasing from early‐ to late‐stage CIN, and furthermore to invasive cervical cancer." (PMID 41362277, 2026). "According to another study, CDKN2A-mediated AKT phosphorylation influences cervical cancer malignancy, but there are no relevant studies in HCC." (PMID 36909185, 2023). "We aimed to investigate the expression and clinical significance of cyclin-dependent kinase inhibitor 2A (P16INK4A), sex determining region Y-box 2 (SOX2), and Aldehyde dehydrogenase 1 family, member A1 (ALDH1A1) in cervical cancer treated with radiotherapy and cervical cell line models." (PMID 30150594, 2018). "Furthermore, based on the GSE168652 dataset of single‐cell RNA sequencing results of human cervical cancer tissues, we recognized six cancer cell subclusters, which were characterized by negative PTPRC (a marker of immune cells) and positive CDH1, CDKN2A, and EPCAM (markers of epithelial cells)." (PMID 36999964, 2023). "Therefore, the decrease in methylation of CDKN2A may lead to reduced protein levels of p16INK4A and HPV E7 oncoprotein, thereby inhibiting cervical cancer progression." (PMID 32328088, 2020). "Of the top 10 ranked upregulated genes, 2 have not been previously reported as associated with cervical cancer (NUSAP1, and CDKN3), while the other 8 have been associated with cervical cancer either scantly (SYCP2, PRC1, CCNB2 and CDC20) or widely (MKI67, CDKN2A, CDC2, and PCNA)." (PMID 23405241, 2013). "The negative correlation of MEG3 with CDKN2A is consistent with literature reports that suggest that the downregulation of MEG3 and overexpression of CDKN2A in cervical cancer is involved in disease progression." (PMID 37628839, 2023).
colorectal cancer (121 papers, 2004 to 2026). A primary or metastatic malignant neoplasm that affects the colon or rectum. "Decreased expression or loss of function of CDKN2A is frequently observed in colorectal cancer and correlates with poor prognosis." (PMID 39120548, 2024). "The upregulation of the CDKN2A gene is notably observed in colorectal cancer, and this increased expression has been associated with unfavorable overall survival (OS) and disease-free survival (DFS) outcomes." (PMID 37950153, 2023). "For instance, it has been shown that hypermethylation in the gene body or 3’UTR region of the CDKN2A gene are associated with higher CDKN2A expression and hence with a worse prognosis in meningioma as well as other malignancies such as colorectal cancer." (PMID 38017560, 2023). "EMT at the invasive front of colorectal cancer is associated with the enhanced expression of the CDKN2A gene product p16INK4A, which correlates with low survival rates." (PMID 37259089, 2023). "In the context of colorectal cancer, a study conducted by Farzad Rahmani investigated the association between a specific single-nucleotide (SNP) polymorphism rs10811661 in the CDKN2A/B gene and the risk of colorectal cancer." (PMID 38137564, 2023). "In conclusion, this study effectively discerned CDKN2A as a biomarker linked to immunity and PD-1 in colorectal cancer." (PMID 37950153, 2023). "Colorectal cancer, one of the most common DNA methylated cancers, exhibits decreased expression of the cyclin‐dependent kinase inhibitor 2A (CDKN2A) and Ras association (RalGDS/AF‐6) domain family member 1 (RASSF1A)." (PMID 34133843, 2022). "CDKN2A is the gene encoding the cell cycle inhibitor p16CDKN2A, and the expression level of p16CDKN2A is closely related to colorectal cancer invasion or metastatic potential." (PMID 36195876, 2022). "MSI-H was also strongly associated with CIMP-H in sporadic colorectal cancers, as expected, and with concurrent CDKN2A/MCC methylation." (PMID 34298744, 2021). "EMAST ≥3/5 was strongly associated with CIMP-H and concurrent MCC/CDKN2A promoter methylation in sporadic colorectal cancer." (PMID 34298744, 2021). "In this current study, we aimed to evaluate the possible relationship between a CDKN2A/B, single nucleotide polymorphisms (SNP) (rs10811661), with the risk of colorectal cancer." (PMID 33122978, 2020). "In order to investigate the correlation between CDKN2A/B polymorphism, rs10811661, and susceptibility to colorectal cancer, genotyping was performed on genomic DNAs obtained from whole blood leukocytes." (PMID 33122978, 2020). "In summary, our findings indicate that the rs10811661 polymorphism of the CDKN2A/B gene was strongly related to the occurrence of colorectal cancer suggesting its potential role as a prognostic biomarker for the management of colorectal cancer." (PMID 33122978, 2020). "In conclusion, our results suggest a relationship between a polymorphism at the CDKN2A/B gene (rs10811661) locus and a poor prognosis in patients with colorectal cancer." (PMID 33122978, 2020). "We have recently reported that concurrent methylation in NEUROG1 and CDKN2A (p16) is associated with higher recurrence in colorectal cancer patients whereas CIMP classification based on the number of methylated markers was not." (PMID 26157509, 2015). "In this study, CIMP-high did not have a prognostic role; however, concurrent methylation in NEUROG1 and CDKN2A (p16) was independently associated with poor survival in colorectal cancer patients treated with adjuvant FOLFOX." (PMID 26157509, 2015). "Additionally, mutations in BRCA2 and CDKN2A have been associated with the pathogenesis of colorectal cancer." (PMID 40447784, 2025). "Furthermore, CDKN2A is associated with poor prognosis in various cancers, including colorectal cancer, yet the underlying causes remain elusive." (PMID 38888512, 2024).
colorectal cancer (continued). "Our results provide novel insights into the role of CDKN2A in cuproptosis resistance and tumor progression, which have important implications for developing more effective diagnostic and therapeutic strategies for colorectal cancer." (PMID 38888512, 2024). "By utilizing the GEO database, a Fisher test was conducted on the GSE40967 dataset, which consists of information from 585 colorectal cancer patients, to investigate the association between the high and low expression groups of CDKN2A with clinicopathological features." (PMID 37950153, 2023). "The presence of the rs10811661 polymorphism in the CDKN2A/B gene may increase the risk of colorectal cancer." (PMID 38137564, 2023). "The gene CDKN2A was reported to be closely associated with colorectal cancer prognosis." (PMID 36132144, 2022). "Thus, we aimed to explore the association of CDKN2A/B gene (rs10811661) polymorphism in Iranian colorectal cancer patients." (PMID 33122978, 2020). "CDKN2A/p16 methylation has been the subject of several studies, and two recent meta-analyses including over 3000 patients with colorectal cancer have revealed a strong association of CDKN2A/p16 methylation with adverse survival, lymph node metastasis and lymphovascular invasion." (PMID 26203306, 2015). "In the CSRS model, cyclin-dependent kinase inhibitor 2A (CDKN2A), also known as p16, is a robust cellular senescence marker that has been identified with high expression in colorectal cancer tissues." (PMID 41614944, 2026). "It inhibits colorectal cancer cell growth by promoting CDKN2A gene demethylation, suppressing NF-κB activity, and enhancing histone acetylation." (PMID 40239010, 2025). "Studies have demonstrated an increase in CDKN2A levels in colorectal cancer cell lines following treatment with elesclomol-Cu." (PMID 38888512, 2024). "By analyzing colorectal cancer cell lines, we observed that 5-FU-sensitive cell lines have the characteristic of high CDKN2A expression during chemotherapy and radiotherapy." (PMID 38888512, 2024). "Higher chromatin accessibility levels were observed in colorectal cancer epithelial cells compared to normal epithelial cells within the CDKN2A gene region." (PMID 38888512, 2024). "To visually examine the spatial expression pattern of CDKN2A in colorectal cancer, we analyzed samples using spatial transcriptomics." (PMID 38888512, 2024). "These distributional patterns suggest localized and heterogeneous overexpression of CDKN2A in the epithelium of colorectal cancer." (PMID 38888512, 2024). "Radiation and chemotherapy are expected to potentially serve as therapeutic approaches for cuproptosis-resistant colorectal cancer with high CDKN2A expression." (PMID 38888512, 2024). "Our findings suggest the existence of an SNHG7/miR-133b/CDKN2A network that potentially acts to inhibit cuproptosis in colorectal cancer." (PMID 38888512, 2024). "In order to investigate the relationship between the clinical application value of CDKN2A in colorectal cancer, we conducted survival analysis and found that patients with high expression of CDKN2A had worse survival prognosis." (PMID 38888512, 2024). "Previous pan-cancer study of cuproptosis-associated genes based TCGA data revealed universal upregulation of CDKN2A across 16 different cancer types, including colorectal cancer." (PMID 38888512, 2024). "To elucidate potential mechanisms driving CDKN2A upregulation in colorectal cancer, we examined epigenetic modification and transcriptional regulation." (PMID 38888512, 2024). "ESTIMATE analysis was conducted to determine how CDKN2A affects the tumor microenvironment (TME) in colorectal cancer." (PMID 37950153, 2023). "The CDKN2A gene plays a significant role in the development of colorectal cancer and biliary tract cancer." (PMID 38137564, 2023).
colorectal cancer (continued). "Colorectal cancer tissues exhibited a significantly elevated level of CDKN2A mRNA expression compared to normal tissues, as confirmed through bioinformatic analysis and clinical observations." (PMID 37950153, 2023). "Different from that study, in this study we analyzed the relationship between CDKN2A and colorectal cancer metastasis from EMT." (PMID 35311137, 2022). "The expression of CDKN2A in small intestine adenocarcinoma is significantly different from that in colorectal cancer, but the expression of CDKN2A in GC is significantly different." (PMID 36249422, 2022). "It has been reported that the expression of the ferroptosis gene CDKN2A is related to the overall survival rate of human colorectal cancer." (PMID 36077637, 2022). "The hypermethylation of the promoter region of CDKN2A has been shown in many cancer types including colorectal cancer." (PMID 36505872, 2022). "Some reports suggest that hypermethylated CDKN2A is a predictor of poor prognosis of colorectal cancer." (PMID 35311137, 2022). "This study has shown that the high methylation phenotype CIMP-H and concurrent MCC/CDKN2A methylation are rare in colorectal carcinomas that are positive for only one EMAST marker or MSI-L but more common in cancers with ≥2 markers." (PMID 34298744, 2021). "In this study we evaluated CDKN2A methylation using pyrosequencing on a large cohort of 422 patients with colorectal cancer." (PMID 22925370, 2012). "In a first step, colorectal cancers and corresponding normal tissue from 432 patients were evaluated for CDKN2A methylation." (PMID 22925370, 2012). "Methylation of CDKN2A in colorectal cancers was significantly more frequent in right-sided colon cancers (p < 0.0001), as well as those with mucinous histology (p = 0.0209), higher tumor grade (p < 0.0001) and lymph node metastasis (p = 0.0335)." (PMID 22925370, 2012). "In a second step, we evaluated the impact of CDKN2A methylation on clinical outcome in a series of 432 patients with colorectal cancers." (PMID 22925370, 2012). "This non-negligible methylation pattern suggests that the normal corresponding mucosa must be used as a control in the assessment of CDKN2A hypermethylation in colorectal cancers." (PMID 22925370, 2012). "CDKN2A promoter hypermethylation has been described in 12-51% of colorectal cancers and is often included in the panel of markers used to assess the CIMP phenotype." (PMID 22925370, 2012). "Previously, high expression of CDKN2A was correlated with a low proliferation of colorectal carcinomas at the invasion front." (PMID 21283756, 2011). "Expression of CDKN1A, which was previously shown to increase with 5-AzaC treatment and of CDKN2A, a gene known to be frequently methylated in colorectal cancers, were used as positive controls and showed increased transcription in most cell lines." (PMID 21079778, 2010). "The study demonstrated that DNMT1 deletion in colorectal cancer cells led to an upregulation of TET2 expression, re-expression of tumour suppressor proteins (p16ink4A and p15ink4B), CDKN2A promoter demethylation, and associated resistance to DNMTi in DNMT1-deleted cells." (PMID 40011240, 2025). "The apoptosis rate of cells was significantly elevated after CDKN2A knockdown in comparison to a low apoptosis rate in the control group, suggesting that CDKN2A may play a crucial role in the survival of colorectal cancer cells by inhibiting apoptosis." (PMID 39950044, 2025). "Studies have shown that CDKN2A may promote the metastasis of colorectal cancer cells by inducing epithelial-mesenchymal transition (EMT)." (PMID 38573998, 2024). "The spatial mapping demonstrated distinct patterns of CDKN2A expression in colorectal cancer." (PMID 38888512, 2024). "Notably, in colorectal cancer, CDKN2A has been found to promote disease progression by facilitating epithelial-mesenchymal transition." (PMID 38888512, 2024). "CDKN2A knockdown significantly downregulated Wnt genes in colorectal cancer cell lines." (PMID 38888512, 2024).
colorectal cancer (continued). "Our research posits that in forthcoming endeavors, the judicious combination of CDKN2A inhibitors with cuproptosis inducers may hold therapeutic potential for the treatment of colorectal cancer." (PMID 38888512, 2024). "This provides a basis for using CDKN2A in colorectal cancer diagnosis, treatment, and prognosis." (PMID 38888512, 2024). "High rates of CDKN2A HD have been identified in several neoplasms, including pleural mesothelioma, pancreatic ductal adenocarcinoma, malignant peripheral nerve sheath tumor, cutaneous melanoma, and colorectal carcinoma, among others." (PMID 39042515, 2024). "Consequently, the stromal score, immune score, and ESTIMATE score of colorectal cancer (CRC) tumors were computed, revealing a positive correlation between CDKN2A and the risk score, as well as the presence of stromal cells and immune cells." (PMID 37950153, 2023). "Furthermore, a positive correlation was observed between the expression of CDKN2A and various immune checkpoint genes in colorectal cancer, namely PDCD1, CTLA-4, and CD274." (PMID 37950153, 2023). "These outcomes imply that CDKN2A might exert its influence on the immune microenvironment in colorectal cancer by means of immune cells or tumor-infiltrating lymphocytes (TILs), aligning with prior investigations." (PMID 37950153, 2023). "Meanwhile, CDKN2A may facilitate colorectal cancer cell metastasis through the induction of EMT and may be associated with the infiltration status of multiple immune cells." (PMID 37350934, 2023). "In this study, bioinformatics analysis showed that CDKN2A(p14) was an independent prognostic factor of colorectal cancer, and its high expression could induce EMT and mediate adverse clinical outcomes in CRC patients." (PMID 35311137, 2022). "A meta-analysis suggests that CDKN2A hypermethylation may be a predictor of poor prognosis in patients with colorectal cancer." (PMID 36338763, 2022). "CDKN2A (p16) is an important cell cycle regulator that is silenced in ~30% of colorectal cancers." (PMID 34298744, 2021). "In colorectal cancers, the CDKN2A, CDK4/6, Rb signaling cascade might also control tumourigenesis driven by loss of wild type APC function." (PMID 30655555, 2019). "To test this concept further, we utilised two cell lines with basally high mTORC1 signalling: the NCI-H460 large cell lung cancer cell line which has PI3KCA, CDKN2A, STK11 and KRAS mutations and the HCT116 colorectal cancer cell line, which contains an activating RAS mutation and PIK3CA mutation." (PMID 28415776, 2017). "Although the functional role of promoter methylation in NEUROG1 and CDKN2A (p16) is inconclusive, CDKN2A (p16) promoter methylation was associated with poor survival in stages II and III colorectal cancer patients who received adjuvant fluoropyrimidine-based chemotherapy." (PMID 26157509, 2015). "The prognostic significance of CDKN2A inactivation in colorectal cancer has been studied, but no clear associations has been found." (PMID 25879218, 2015). "To conclude, our study indicates that pyrosequencing for CDKN2A methylation analysis is robust even at low methylation levels and may be particularly suited for large solid tumor samples like colorectal cancer." (PMID 22925370, 2012). "Furthermore, experimental study has demonstrated that baicalin prevents colorectal cancer by inhibiting CDKN2A, suggesting that targeting senescence markers may suppress tumor development." (PMID 41614944, 2026). "Moreover, thorough examinations of immune infiltration and biological functionalities have demonstrated the potential of CDKN2A as a viable therapeutic target for colorectal cancer and may offer valuable insights for PD-1-mediated immunotherapy." (PMID 37950153, 2023). "The results showed that, compared with normal tissues, the expression of ADRA1B, CDKN2A, FCER2, and IL13 was significantly upregulated in colorectal cancer tissues, while CALM1, CTNNA1, GSR, INSR, and MAPK9 were significantly downregulated." (PMID 40696679, 2025).